HSD17B4 (hydroxysteroid 17-beta dehydrogenase 4)
Description:
Bifunctional enzyme acting on the peroxisomal fatty acid beta-oxidation pathway. Catalyzes two of the four reactions in fatty acid degradation: hydration of 2-enoyl-CoA (trans-2-enoyl-CoA) to produce (3R)-3-hydroxyacyl-CoA, and dehydrogenation of (3R)-3-hydroxyacyl-CoA to produce 3-ketoacyl-CoA (3-oxoacyl-CoA), which is further metabolized by SCPx. Can use straight-chain and branched-chain fatty acids, as well as bile acid intermediates as substrates. May play a role in peroxisomal beta-oxidation step in polyunsaturated fatty acids (PUFAs) biosynthesis. Possibly regulates systemic levels of docosahexaenoic acid (DHA, C22:6n-3) through a process involving endoplasmic reticulum desaturation and elongation of alpha-linolenic acid (ALA, C18:3n-3) to form tetracosahexaenoic acid (THA, C24:6n-3), which is then beta-oxidized to DHA in peroxisomes.
Synonyms: MFE-2; DBP; MFP-2; SDR8C1; MPF-2; PRLTS1
Tractability: Small molecule: a structure with a bound ligand is known; it has a high-quality binding pocket. PROTAC: ubiquitination databases record sites on it; its protein half-life has been measured.
Target class: Enzyme; Oxidoreductase
Gene: Protein-coding gene on chromosome 5 (119,452,465 to 119,637,199, forward strand). Ensembl gene ENSG00000133835.
Subcellular location: Peroxisome
Subcellular location (Human Protein Atlas): Peroxisomes
Pathways (Reactome):
Metabolism: Beta-oxidation of pristanoyl-CoA; Beta-oxidation of very long chain fatty acids; Synthesis of bile acids and bile salts via 7alpha-hydroxycholesterol; alpha-linolenic acid (ALA) metabolism
Protein localization: Peroxisomal protein import; TYSND1 cleaves peroxisomal proteins
Gene Ontology:
Molecular function: (3R)-3-hydroxyacyl-CoA dehydrogenase (NAD+) activity; 3-hydroxyacyl-CoA dehydratase activity; enoyl-CoA hydratase activity; estradiol 17-beta-dehydrogenase [NAD(P)+] activity; protein homodimerization activity; (2E)-enoyl-CoA hydratase activity; (3S)-3-hydroxyacyl-CoA dehydrogenase (NAD+) activity; 3alpha,7alpha,12alpha-trihydroxy-5beta-cholest-24-enoyl-CoA hydratase activity; oxidoreductase activity, acting on the CH-OH group of donors, NAD or NADP as acceptor; very-long-chain (3R)-3-hydroxyacyl-CoA dehydratase activity
Biological process: androgen metabolic process; estrogen metabolic process; fatty acid beta-oxidation; medium-chain fatty-acyl-CoA metabolic process; osteoblast differentiation; very long-chain fatty-acyl-CoA metabolic process; fatty acid beta-oxidation using acyl-CoA oxidase; fatty acid biosynthetic process; lipid metabolic process
Cellular component: membrane; peroxisomal membrane; peroxisome; cytosol; peroxisomal matrix
Genetic constraint (gnomAD): Loss-of-function variants: 14 observed, 25.62 expected, observed/expected ratio (o/e) 0.55, 90% interval 0.36 to 0.85. The upper end of that interval is the gene's LOEUF score, 0.85, which puts it in group 3 of 6, group 1 being the genes least tolerant of losing a copy. Missense variants: 433 observed, 397.13 expected, observed/expected ratio (o/e) 1.09, 90% interval 1.01 to 1.18. Synonymous variants: 149 observed, 137.11 expected, observed/expected ratio (o/e) 1.09, 90% interval 0.95 to 1.25.
Gene-disease validity (ClinGen):
ClinGen rates the evidence that HSD17B4 causes each of these diseases.
d-bifunctional protein deficiency (autosomal recessive): Definitive. A genetic disorder that affects the ability of the body to effectively break down fat from our diet.
Perrault syndrome (autosomal recessive): Definitive. Perrault syndrome (PS) is characterized by the association of ovarian dysgenesis in females with sensorineural hearing impairment.
Homologues: Orthologues: chimpanzee HSD17B4 (99% identical), macaque HSD17B4 (97% identical), rabbit HSD17B4 (90% identical), rat Hsd17b4 (87% identical), mouse Hsd17b4 (86% identical), dog HSD17B4 (86% identical), pig HSD17B4 (85% identical), guinea pig HSD17B4 (82% identical), tropical clawed frog hsd17b4 (69% identical), zebrafish hsd17b4 (68% identical), Drosophila melanogaster Mfe2 (43% identical), Caenorhabditis elegans dhs-28 (30% identical). Paralogues in human: HSD17B8 (11% identical), SDR16C5 (11% identical), HSD17B10 (10% identical), HSD17B2 (10% identical), HSD17B1 (10% identical), RDH10 (9% identical), RDH16 (9% identical), HSD17B13 (9% identical), RDH5 (9% identical), DHRS3 (9% identical), HSD11B2 (9% identical), HSD17B6 (9% identical), and 13 more.
Diseases named in the same sentence as HSD17B4 in open-access papers:
HSD17B4 is named in the same sentence as 80 diseases in open-access papers, as found by Europe PMC text mining. Sharing a sentence is not in itself a finding about the gene and the disease. The quoted sentences say what the papers report.
prostate carcinoma (18 papers, 2010 to 2025). A carcinoma that arises from epithelial cells of the prostate gland. "There is evidence that HSD17B4 is associated with a variety of cancers, including liver cancer, ovarian cancer, and prostate cancer, making it a potential therapeutic target." (PMID 38406279, 2024). "The overexpression of Hsd17b4 in human studies has been linked to prostate cancer, suggesting its potential as a biomarker for androgen metabolism." (PMID 38396857, 2024). "Overexpression of HSD17B4 was noted in prostate cancer with significant association with worsened prognosis via possibly steroid metabolism and fatty acid oxidation." (PMID 29383116, 2017). "Additionally, loss of function (LoF) of HSD17B4 drives androgenesis in prostate cancer and is linked to the development of castration-resistant prostate cancer." (PMID 39038933, 2024). "In addition, HSD17B4 overexpression has been reported to be associated with aggressive phenotypes in liver and prostate cancers." (PMID 28186977, 2017). "Overexpression of HSD17B4 has been observed in various cancers, including prostate cancer, hepatocellular carcinoma, and breast cancer." (PMID 37108962, 2023). "HSD17B4 expression is known to increase in castration resistant prostate cancer, leading to metabolic re-programming resulting in AR-stimulation and poor prognosis." (PMID 35563746, 2022). "For instance, it was reported that HSD17B4 (hydroxysteroid 17-beta dehydrogenase 4) overexpression promotes proliferation and malignancy of prostate cancer cells." (PMID 35317831, 2022). "Recently, HSD17B4 has been shown to be expressed highly in prostate cancer cells and prostate tissues from prostate cancer patients, and the level of expression was related to the progression of cancer." (PMID 34858832, 2021). "RT-PCR analyses using a downstream primer showed the presence of a novel transcript (V6, tentatively), and the transcript was the major transcript of HSD17B4 in breast and prostate cancer cell lines." (PMID 32968149, 2020). "For example, in prostate cancer cells, the up-regulation of HSD17B4, a protein involved in fatty acid oxidation, is correlated with tumor progression." (PMID 33643916, 2020). "It has been observed that increased expression of HSD17B4 is correlated with poor prognosis in prostate cancer." (PMID 30704450, 2019). "Notably, the regulatory mechanism of HSD17B4 with its related interactors provides new insight into prostate cancer progression and indicates that androgen metabolic enzymes are potential biomarkers." (PMID 32678070, 2020). "However, it was shown that deacetylation processes that are predominant in prostate cancer protects HSD17B4 from CMA degradation and contributes with cancer progression." (PMID 33643916, 2020). "hsd17b4 is a potential biomarker for the diagnosis of prostate cancer (PCa), and studies implicate an increase in hsd17b4 expression related to poor prognosis for prostate cancer, upregulating hsd17b4 enhanced the malignant capacities of PCa cells, while hsd17b4 knockdown inhibited these capacities." (PMID 37904220, 2023). "In breast and prostate cancers, CREBBP and SIRT3 regulate HSD17B4 acetylation at K669, which facilitates HSPA8-mediated CMA degradation, reducing HSD17B4 accumulation and suppressing migration and invasion." (PMID 41213956, 2025). "Acetylation of HSD17B4 promotes its degradation by CMA and leads to a subsequent decrease in prostate cancer progression." (PMID 35317831, 2022).
Perrault syndrome (14 papers, 2012 to 2025). "Mutations in HSD17B4 are linked to Perrault syndrome, which is associated with hearing loss and intellectual disability, and D-bifunctional protein deficiency, a fatty acid metabolic disorder." (PMID 40725187, 2025). "Homozygous and compound heterozygous mutations of the HSD17B4 gene produce autosomal recessive D-BPD or Perrault syndrome." (PMID 38732138, 2024). "In roof/epithelial (CD−M1), Myo6 and Actg1 were associated with nonsyndromic hearing loss (NSHL), Hsd17b4 with Perrault syndrome, Ednrb and Edn3 with Waardenburg syndrome, and Actg1 with Baraitser–Winter syndrome." (PMID 39684410, 2024). "Among these there were two SNVs located in noncoding regions (GM79, RMRP, associated with cartilage-hair hypoplasia and GM275, HSD17B4, associated with Perrault syndrome)." (PMID 38909121, 2024). "The HSD17B4 gene is directly linked to neurological disorders such as Perrault syndrome, which is inherited in an autosomal recessive manner." (PMID 38539661, 2024). "Our findings supported that HSD17B4 was one of the genes contributing to Perrault syndrome with the likely pathogenic variant c.298G > T (p.A100S)." (PMID 28830375, 2017). "Compound heterozygous mutations in HSD17B4 have also been reported in two sisters diagnosed with Perrault syndrome (MIM # 233400), who presented in adolescence with ovarian dysgenesis, hearing loss, and ataxia." (PMID 24602372, 2014). "This CNV contains 10 genes including HSD17B4, mutations of which cause Perrault Syndrome with ataxia indicative of cerebellar involvement." (PMID 24098143, 2013). "Recessive HSD17B4 mutations were more recently identified as the cause of Perrault syndrome (OMIM #233400) in two sisters who fulfilled the defining features of the syndrome (ovarian dysgenesis and sensorineural deafness) and who also presented with peripheral neuropathy and ataxia." (PMID 24602372, 2014). "Furthermore, it points to crosstalk between mitochondria and peroxisomes in HSD17B4-deficiency and Perrault syndrome." (PMID 24602372, 2014). "Our newly proposed subtype of DBP deficiency (type IV) would also apply to two sisters recently diagnosed with Perrault syndrome caused by compound heterozygous mutations within HSD17B4, one affecting the dehydrogenase domain and one the hydratase domain, similar to our patients." (PMID 23181892, 2012). "Determination of the segregation status of the parents of a proband with a rare compound heterozygote in the gene HSD17B4 will help the genetic counselling for the prognosis of Perrault syndrome in the family." (PMID 38249302, 2024). "It is noteworthy that none of the Perrault syndrome disease proteins were dysregulated, except HSD17B4 that showed a significant upregulation only in patient fibroblasts, meaning the role of ClpP cannot be explained by abnormal degradation of a Perrault syndrome disease protein, by this dataset." (PMID 34943861, 2021). "However, homozygous variants in HSD17B4 (D-bifunctional protein deficiency (MIM# 261515), Perrault syndrome 1 (MIM# 233400)) and ACOX2 (Bile acid synthesis defect, congenital (MIM# 617308)) have reliably been associated with monogenic diseases." (PMID 31533369, 2019). "In addition to well-established Perrault syndrome genes involved in mitochondrial function, recent studies have described causative variants in non-mitochondrial genes including HSD17B4, GGPS1 and PEX6 in patients presenting with clinical features overlapping with Perrault syndrome." (PMID 37148394, 2023).
Ataxia (8 papers, 2013 to 2025). Ataxia refers to impaired coordination of voluntary muscle movement. "Compound heterozygous mutations in HSD17B4 also contribute to middle-age-onset spinocerebellar ataxia, with motor, hearing, and speech impairments." (PMID 40725187, 2025). "We, therefore, supplemented the EOAD- control group with ataxia genotypes that were not reported with comorbid dystonia in literature (including ABHD12; IFRD1; KIAA0226; PHYH; TDP1; VWA3B; GTF2H5; FLVCR1; ACO2; HSD17B4; DNAJC3 gene mutations; PubMed and OMIM)." (PMID 33255407, 2020).
breast carcinoma (8 papers, 2017 to 2023). "In summary, we identified that methylation of the promoter CpG island of HSD17B4 was associated with the pCR of HER2-positive breast cancer to trastuzumab and chemotherapy with a specificity of 79%." (PMID 28186977, 2017). "However, it remains an issue how HSD17B4 silencing is associated with pCR of HER2-positive breast cancer patients after trastuzumab and chemotherapy." (PMID 28186977, 2017). "More importantly, K669 acetylation is inversely correlated with HSD17B4 in human breast cancer tissues." (PMID 33435147, 2021). "This showed that HSD17B4 methylation was a promising marker to predict pCR of HER2-positive breast cancer to HER2-directed therapy." (PMID 32968149, 2020). "Previous studies have suggested that SIRT3 is responsible for acetylation of HSD17B4 in breast cancer cells." (PMID 32678070, 2020). "At the same time, HSD17B4 silencing can be advantageous for some breast cancer cells as it is involved in estrogen catabolism." (PMID 32968149, 2020). "As for subtypes of breast cancer, the TCGA database and our analysis of 134 additional surgical specimens showed that HSD17B4 methylation was enriched in HER2-positive and triple-negative subtypes." (PMID 32968149, 2020). "HSD17B4 was highly expressed in the vast majority of human cancers, and its methylation was present only in breast cancers and one lymphoblastic leukemia cell line." (PMID 32968149, 2020). "In contrast, HSD17B4 methylation-silencing only in some breast cancer cell lines suggested that the silencing can oppositely provide a growth advantage only in breast cancer cells." (PMID 32968149, 2020). "In the present study, we identified that HSD17B4 methylation is a candidate predictive marker of HER2-positive breast cancer to HER2-directed therapy." (PMID 32968149, 2020). "HSD17B4 is overexpressed in various cancers, including breast cancer, hepatocellular carcinoma, colonic cancer and ovarian cancer." (PMID 32678070, 2020). "Importantly, when HER2-positive breast cancer patients were stratified by age, we found that HSD17B4 methylation had a high incidence in patients older than 55 years (40.5%)." (PMID 32968149, 2020). "In conclusion, HSD17B4 methylation was strongly associated with the sensitivity of HER2-positive breast cancer to HER2-directed therapy, and no additional markers were isolated." (PMID 32968149, 2020). "As a marker to predict pCR to trastuzumab and chemotherapy against HER2-positive breast cancer, HSD17B4 methylation was successfully identified by genome-wide methylation analysis, and was validated by analysis of an independent validation set of samples (P < 0.001)." (PMID 28186977, 2017). "Nevertheless, only HSD17B4 methylation was re-validated, showing its importance as a single gene marker for the sensitivity of HER2-positive breast cancers to HER2-directed therapy." (PMID 32968149, 2020). "For instance, several lipid-lowering drug elevated the expression of HSD17B4, which down-regulated in PCOS and down-expression of which indicate poor prognosis in breast cancer." (PMID 29050221, 2017). "In addition to the potential application to surgery-free treatment of HER2-positive breast cancer patients, unmethylated HSD17B4 may be used to identify patients who will not benefit from trastuzumab treatment but might benefit from lapatinib." (PMID 28186977, 2017).
d-bifunctional protein deficiency (5 papers, 2012 to 2025). "D-bifunctional protein deficiency is a rare and serious condition, with diagnosis typically confirmed through HSD17B4 gene sequencing." (PMID 40402439, 2025). "D-bifunctional protein deficiency (D-BPD) is a rare fatal autosomal recessive peroxisomal disorder caused by biallelic pathogenic mutations in the hydroxysteroid 17-beta dehydrogenase 4 (HSD17B4) gene; it is characterized by hypotonia, seizures, and facial dysmorphisms during the neonatal period." (PMID 41282484, 2025). "When HSD17B4 gene mutations cause varying degrees of decline in DBP function, it can lead to D-Bifunctional protein deficiency(D-BPD) which is a rare autosomal recessive discord." (PMID 41567431, 2025).
hepatocellular carcinoma (5 papers, 2017 to 2025). A malignant tumor that arises from hepatocytes. "In hepatocellular carcinoma, HSD17B4 was shown to act as an adaptor between inflammation and cancer cell proliferation." (PMID 29383116, 2017). "HSD17B4 is not only related to steroid synthesis but also proved to be a novel proliferation-promoting gene, whose overexpression or knockout can promote or inhibit, respectively, the proliferation of the human hepatocellular carcinoma cell line HepG2." (PMID 36230445, 2022). "The overexpression of HSD17B4 promotes hepatocellular carcinoma (HCC) cell proliferation." (PMID 34858832, 2021).
X-linked adrenoleukodystrophy (5 papers, 2017 to 2024). X-linked adrenoleukodystrophy (X-ALD) is a peroxisomal disorder resulting in cerebral demyelination, axonal dysfunction in the spinal cord leading to spastic paraplegia, adrenal insufficiency and in some cases testicular insufficiency. "We present the case of an infant with elevated lysophosphatidylcholine C26:0 (C26:0-LPC) levels identified during X-linked adrenoleukodystrophy (ALD) screening, leading to a diagnosis of DBP deficiency due to a homozygous HSD17B4 c.1041T>A, p.(Tyr347Ter) variant." (PMID 39282052, 2024).
Peroxisomal disorders (4 papers, 2019 to 2021).
colorectal cancer (3 papers, 2011 to 2023). A primary or metastatic malignant neoplasm that affects the colon or rectum. "We observed little support for an association of gene variants in hormone receptors (ESR1, ESR2, PGR) and active estrogen synthesizers (HSD17B1, HSD17B2, and HSD17B4) with colorectal cancer risk among postmenopausal women of European descent." (PMID 21627810, 2011). "Moreover, targeted public health campaigns and educational programs can raise awareness of the detrimental effects of alcohol consumption on colorectal cancer risk, especially in the group with HSD17B4 rs721673 (AG/GG) and rs721675 (AT/TT) risk genotypes." (PMID 37108962, 2023). "Colorectal cancer (CRC) is a major public health issue, and there are limited studies on the association between 17β-hydroxysteroid dehydrogenase type 4 (HSD17B4) polymorphism and CRC." (PMID 37108962, 2023). "Our study showed that the expression level of hsd17b4 in colorectal cancer samples with S.japonicum infection was higher than that in pure colorectal cancer samples, indicating a poor prognosis." (PMID 37904220, 2023).
COVID-19 (3 papers, 2023 to 2024). A disease caused by infection with severe acute respiratory syndrome coronavirus 2. "In addition, both ACSL5 and HSD17B4 were found to be associated with fatty acid synthesis, which may indicate the impact of COVID-19 and ICC on lipid metabolism." (PMID 38648205, 2024). "At the genetic level, COVID-19 hospitalization and MS share five risk genes within two loci, including TNFAIP8, HSD17B4, CDC37, PDE4A, and KEAP1, which may mediate the association between MS and COVID-19." (PMID 37395896, 2023).
ovarian carcinoma (3 papers, 2017 to 2024). A malignant neoplasm originating from the surface ovarian epithelium. "HSD17B4 is specifically down-regulated in breast and ovarian cancers among various human cancers, and this suggests that its silencing is associated with sex hormone metabolism and then sensitivity to trastuzumab." (PMID 28186977, 2017).